ATF4 (activating transcription factor 4)
Diseases named in the same sentence as ATF4 in open-access papers (continued):
Sharing a sentence is not in itself a finding about the gene and the disease.
melanoma (65 papers, 2011 to 2026). A malignant, usually aggressive tumor composed of atypical, neoplastic melanocytes. "The antimelanoma activity of IFN-γ relies on diminished protein translation, which is followed by the activation of the stress response associated with the activating transcription factor-4 (ATF-4)high/MITFlow phenotype of melanoma cells." (PMID 40108693, 2025). "GCN2 was found to promote the translation of the transcription factor CREB2/ATF4 to promote MDSCs maturation in a melanoma mouse model, and deficiency of ATF4 and GCN2 reduced tumor growth." (PMID 37277776, 2023). "Using conditional knockout ATF4 mice, we show that global, or fibroblast-specific loss of host ATF4, results in deficient vascularization and a pronounced growth delay of syngeneic melanoma and pancreatic tumours." (PMID 35654839, 2022). "Recently, it has also been reported that the knockout of ATF4 can reduce the resistance of gastric cancer cells to cisplatin or increase the sensitivity of BRAF-mutated melanoma to vemurafenib." (PMID 35864117, 2022). "Glucose and glutamine starvation drives melanoma phenotype switching through the ISR-associated transcription factor ATF4." (PMID 34604096, 2021). "Furthermore, reduced expression of UPR target genes such as XBP1s, ATF4, and BiP was observed in the B2905 mouse melanoma model upon anti-cytotoxic T lymphocyte-associated antigen 4 (CTLA-4) ICI." (PMID 41372991, 2025). "The deficient supply of glycine and proline induced by ATF4 knockout in CAFs leads to significant defects in collagen biosynthesis and a reduced ability to support angiogenesis, so as to result in pronounced growth delay of melanoma." (PMID 36003368, 2022). "Both Atf4 and Ass1 knockout melanomas exhibited enhanced infiltration of Cd8+ T cells and significantly reduced tumor growth in a syngeneic mouse model." (PMID 41867829, 2026). "ATF4 knockout in melanoma cells phenocopied ASS1 knockout in the same cells, both showing greater sensitivity to arginine depletors such as ADI-PEG20." (PMID 41867829, 2026). "Serine/glycine deprivation activates a multi-transcription factor response involving ATF4, FOXC1, and cooperation between BRAFV600E and ATF4 in melanoma to induce PHGDH expression." (PMID 41486146, 2026). "To further validate our approach, we investigated the activation of the ATF4 pathway in human melanoma tumor-infiltrating lymphocytes (TILs)." (PMID 40335738, 2025). "In the B16-F10 melanoma model, PERK-deficient macrophages exhibited impaired M2 polarization coincident with lower levels of ATF4-mediated stimulation of serine biosynthesis, which supported M2 polarization." (PMID 41372991, 2025). "To corroborate the findings from the data mining, we assessed the protein expression of ATF4 in CD3+ T cells infiltrating primary melanoma patient biopsies." (PMID 40335738, 2025). "Pathway score analysis further revealed that, compared with healthy blood T cells, melanoma TILs presented higher exhaustion, ER stress and ATF4 signature scores." (PMID 40335738, 2025). "Subsequently, ERK phosphorylated ATF4, which induced cytoprotective autophagy, leading to melanoma cell survival." (PMID 38297380, 2024). "Both drugs inhibited thapsigargin induced PERK‐dependent phosphorylation of EIF2A and expression of ATF4 in melanoma A375 cells." (PMID 38414326, 2024). "Host mice with ATF4 knockout presented with significant delays in melanoma tumour growth following tumour cell inoculation compared to wildtype hosts." (PMID 36765657, 2023). "Impaired translation is accompanied by an amino acid deprivation-dependent stress response driving activating transcription factor-4 (ATF4)high/microphtalmia-associated transcription factor (MITF)low transcriptomic signatures, also in patient melanomas." (PMID 36812891, 2023). "TINCR downregulation inhibits melanoma development in vivo by suppressing the ATF4-CHOP pathway and activating the Hippo pathway." (PMID 35159386, 2022).
melanoma (continued). "The levels of αSMA, PDGFRβ and FAP in melanoma and pancreatic tumours were nearly undetectable in Atf4Δ/Δ mice, which indicates that ATF4 is essential for CAF activation within the TME." (PMID 35654839, 2022). "TINCR expression prevents translational reprogramming, activation of ATF4, and stress response in melanoma." (PMID 35159386, 2022). "Similar to the results from the melanoma growth model, global host ATF4 ablation resulted in a pronounced delay in tumour growth and extension of overall survival." (PMID 35654839, 2022). "Analyses of human melanoma and pancreatic tumours revealed a strong correlation between ATF4 and collagen levels." (PMID 35654839, 2022). "On contrary, lncRNA TINCR was depleted under the normal oxygen condition, so as to mediate global translational reprogramming and increased proteins synthesis of ATF4 and other integrated stress response, leading to melanoma metastasis." (PMID 36541918, 2022). "This study demonstrates that MAPK inhibitors can synergize with L-asparaginase in a subcutaneous mouse melanoma model through preventing the ATF4 accumulation and ASNS induction." (PMID 34205460, 2021). "ATF4 has been shown to negatively regulate the CRE of the Melanocyte Inducing Transcription Factor (MITF) promoter upon glucose deprivation in melanoma." (PMID 33418948, 2021). "Using scRNA-seq, we identified a role for ATF4 in enabling the escapee phenotype, which we validated in several cell lines as well as in melanoma patient samples." (PMID 33741929, 2021). "In summary, we demonstrated that NLRP1 functions downstream of the MAPK/ERK signaling via ATF4 and is a player of targeted therapy resistance in melanoma." (PMID 33396632, 2020). "Although ATF4 was detected in untreated cells, as observed in melanoma cells growing under low glucose conditions, unexpectedly, we found that ACF consistently induced a decrease in ATF4 protein in melanoma cell lines." (PMID 33396270, 2020). "These two different drug treatments activate distinct signaling pathways that converge on the ATF4/NLRP1 axis to regulate melanoma growth." (PMID 33396632, 2020). "This is the first report to link the MAPK/ERK signaling to NLRP1 in melanoma through the ATF4 regulation." (PMID 33396632, 2020). "miR-205, INPPL1, BTBD3 and ATF4 expression was measured by RT-qPCR in human primary melanoma tissue samples." (PMID 32179834, 2020). "We examined ATF4 mRNA expression in human melanoma tissues using two publicly available microarray datasets from independent gene profiling studies and found that metastatic melanoma tissues display higher ATF4 mRNA level than primary melanoma." (PMID 33396632, 2020). "We provide further evidence that NLRP1 lies downstream of the ER stress signaling cascade, possibly through the PERK/ATF4 in melanoma cells." (PMID 33396632, 2020). "Together, our data strongly suggest that glucose deprivation suppresses MITF expression through ROS induced ATF4 up-regulation, which in turn results in reduced melanoma cell proliferation." (PMID 28380427, 2017). "Our data strongly indicated that glucose restriction inhibits melanoma cell proliferation by inducing ATF4 to subsequently interfere with MITF expression in a CRE dependent manner." (PMID 28380427, 2017). "We found that in the context of glucose deprivation in melanoma, ATF4 negatively regulates the CRE of the MITF promoter." (PMID 28380427, 2017). "Similar regulatory mechanisms of ATF4 by METTL5 were also reported in melanoma cell lines." (PMID 41042068, 2025). "Consistent with our in vitro findings, genes associated with the ATF4 (e.g., ATF4, DDIT3, PPP1R15A and CHAC1), ATF6 (e.g., ATF6B, CALR, SEL1L, and EDEM1) and XBP1 (e.g., SSR3 and DELR1) pathways were significantly enriched in melanoma TILs compared with healthy blood T cells." (PMID 40335738, 2025).
melanoma (continued). "For example, the lncRNA terminal differentiation-induced non-coding RNA (TINCR) inhibits the invasive phenotype of melanoma, partly through the regulation of activating transcription factor 4 (ATF4), a stress-response factor that can regulate protein translation, enhancing invasion." (PMID 41463281, 2025). "The gene PSAT1, together with ATF4 and NRF2, is associated with thiol starvation in melanoma." (PMID 38785552, 2024). "Thus, thapsigargin induced a PERK‐dependent ER‐stress response in melanoma cells that included upregulation of ATF4." (PMID 38414326, 2024). "Additionally, this study observed that AsC treatment inhibited the expression of p-eIF2α and ATF4 in lung cancer and melanoma cells after 36 h." (PMID 38132921, 2023). "Finally, immunofluorescence staining of human melanoma tissues revealed that in addition to tumour cells, ATF4 is highly expressed in CAFs (αSMA) that localized to the perivascular area (CD34)." (PMID 35654839, 2022). "Interestingly, ATF4/NLRP1 regulation by the MAPK/ERK pathway uses distinct mechanisms in melanoma cells before and after the acquired resistance to targeted therapy." (PMID 33396632, 2020). "Since ACF, by inhibiting HIF-1α-regulated pathways in normoxia, can reduce glucose availability and induce ER stress while suppressing ATF4 protective pathways, this drug could represent an efficient treatment against melanoma." (PMID 33396270, 2020). "Nevertheless, the observation that ACF indirectly targets ATF4 in melanoma cells could be interesting from a therapeutic point of view." (PMID 33396270, 2020). "To understand the relationship between the MAPK/ERK pathway and NLRP1, we tested whether ATF4 works upstream of NLRP1 expression in metastatic melanoma cells." (PMID 33396632, 2020). "In fact, we observed that ACF dramatically decreased the protein levels of ATF4 in melanoma cells." (PMID 33396270, 2020). "Since p-eIF2α reduces general translation initiation while facilitating the preferential translation of select transcripts such as that encoding ATF4, the results seem to indicate that ACF may lead to a destabilization of ATF4-protein in melanoma cells." (PMID 33396270, 2020). "Indeed, we demonstrated that NLRP1 plays a role in vemurafenib resistance in melanoma through transcriptional regulation by ATF4, in which activation is mediated by the MAPK/ extracellular signal-regulated kinase pathway." (PMID 32899791, 2020). "Interestingly, experiments designed to increase p-eIF2α with salubrinal, a specific inhibitor of eIF2α phosphatase, also seem to indicate that ACF induced destabilization of ATF4 protein in melanoma cells." (PMID 33396270, 2020). "It has been reported that MAPK inhibitor-resistant SK-MEL-28 cells have a decreased expression ratio of melanocyte-inducing transcription factor (MITF) to AXL receptor tyrosine kinase, a marker of targeted therapy resistance in melanoma, which is possibly driven by increased ATF4 expression." (PMID 33396632, 2020). "Thus, as phosphorylated eIF2α inhibits eIF2B, this global reprogramming of translation involving high expression of ATF4 leads to invasiveness in melanoma cells." (PMID 29369499, 2018). "Indeed, glucose restriction resulted in a strong up-regulation of ATF4 in melanoma cells, and this correlated with reduced MITF expression." (PMID 28380427, 2017). "Together with recent reports suggesting that fasting cycles can significantly affect tumour growth and responses to chemotherapy it will be of upmost interest to determine the role of ATF4 in all these processes and the interplay between ATF4 and the master regulator of melanoma biology MITF." (PMID 28380427, 2017). "However, ATF4 only bound to the MITF promoter when glucose levels in melanoma cells were restricted." (PMID 28380427, 2017).
melanoma (continued). "Importantly, lower levels of XBP1s, ATF4, and BiP expression in pre-treatment tumor biopsy samples significantly correlated with better treatment responses and prolonged survival in different groups of melanoma patients undergoing anti-CTLA-4 therapy." (PMID 41372991, 2025). "Unlike melanoma cells, CO cells showed limited upregulation of ATF4 and GADD153 in response to NGLY1 loss, suggesting that NGLY1 dysfunction may cause distinct types or levels of stress in different cells." (PMID 35322011, 2022). "Thus, ATF4-mediated phenotype switching might occur early as melanoma cells are adapting to MAPKi therapy." (PMID 34604096, 2021). "Interestingly, melanoma cells grown at this glucose concentration, corresponding to fasting physiological concentrations, exhibit a high rate of ROS production, which leads to the activation of ATF4." (PMID 33396270, 2020). "Since ATF4 is a poor drug target, but plays important functions in cancer progression and resistance to therapy, the action of a small molecule such as ACF that indirectly targets ATF4 for proteasomal degradation could open new avenues for the treatment of melanoma." (PMID 33396270, 2020). "It has been demonstrated that δ-TT triggers cell death and activates ER stress-related pathways such as PERK/p-eIF2α/ATF4/CHOP and IRE1α to induce apoptosis in melanoma cells and that δ-TT significantly inhibits tumor growth rate in A375 melanoma animal model." (PMID 40932870, 2025). "Melanoma cells exhibit IL-1β-driven autoinflammatory properties, partially regulated by the MAPK/ERK pathway and transcription factor ATF4." (PMID 40558540, 2025). "In melanoma, IL-1β secretion is partially regulated by the MAPK/ERK pathway via the transcription factor ATF4." (PMID 40558540, 2025). "As with thapsigargin, WX8 induced PERK‐dependent phosphorylation of EIF2A protein and upregulation of ATF4 and DDIT3 proteins in melanoma A375 cells accompanied by translocation of transcription factors ATF4 and CEBPb to the nucleus." (PMID 38414326, 2024). "Together, these results indicate that host ATF4 acts as a driving factor in the development of the metastatic niche and efficient metastatic process in B16F10 melanoma tumours." (PMID 35654839, 2022). "In this study, we uncovered an essential role for the master ISR effector ATF4 in shaping CAF functionality to dictate ECM organization and angiogenesis to support a tumour-promoting phenotype in experimental models of melanoma and pancreatic cancer." (PMID 35654839, 2022). "While NGLY1 malfunction appeared to upregulate ATF4 in WA09 COs, this upregulation was moderate, compared with that in NGLY1-knockdown melanoma cells." (PMID 35322011, 2022). "In human melanoma cells, when the synthesis of aspartate is inhibited, the GCN2/ATF4 pathway is activated to increase glutamine uptake by upregulating SLC1A5." (PMID 35864117, 2022). "Other regulatory factors, such as ATF4, or HIF, bind to the promoter of PCK2 to enhance its transcription in breast and cervix carcinomas or melanoma, respectively." (PMID 37304670, 2021). "Kinetic analysis in MDA-MB-435S melanoma cells, showed that C/EBPδ induction peaked between 4–8 h, relatively concurrent with XBP1S, ATF4 and CHOP." (PMID 34725321, 2021). "We next examined the levels of ATF4 in the controls and melanoma cells subjected to ACF treatments, since in contrast to global translation, which is downregulated by eIF2α phosphorylation, ATF4 translation is increased." (PMID 33396270, 2020). "Interestingly, we show that acriflavine targets activating transcription factor 4 (ATF4) for proteasomal degradation while suppressing the expression of microphthalmia-associated transcription factor (MITF), a master regulator of melanocyte development and a melanoma oncogene." (PMID 33396270, 2020). "In the presence of TG, both ATF4 and NLRP1 were upregulated at mRNA levels (respectively), suggesting that NLRP1 expression responds to ER stress activation in melanoma cells." (PMID 33396632, 2020).
melanoma (continued). "In parental melanoma cells, the RSK2/ATF4 axis acts as the hub between the MAPK/ERK signaling and NLRP1; however, MAPK inhibitor-resistant cells seem to lose this signaling hub and switch to the cAMP/PKA pathway to redirect NLRP1 expression." (PMID 33396632, 2020). "The level of transcription factor ATF4, a downstream target of PERK in the PERK–eIF2α pathway, was also increased after treatment in A2058 and A375 melanoma cells." (PMID 29734677, 2018). "For example, in BRAF inhibitor‐sensitive melanoma cell lines, the preclinical version of vemurafenib, PLX4720, led to a rapid induction of ATF‐4." (PMID 29193645, 2018). "Exposure of melanoma cells to imiquimod induces the phosphorylation of PERK and IRE1α, and both the expression and phosphorylation of ATF‐4 together with expression of GRP78 protein." (PMID 26578344, 2016). "In melanoma cells, δ-TT exerted its antitumor effect through activation of the PERK/p-eIF2α/ATF4/CHOP, IRE1α and caspase-4 ER stress-related branches." (PMID 27461002, 2016). "The transcription factor ATF4, a downstream signal of PERK-eIF2α pathway, was increased after 11-dehydrosinulariolide treatment in A2058 melanoma cells." (PMID 23015779, 2012). "To elucidate which mechanisms are responsible for the synergistic cytotoxic effect observed when treating melanoma cells with 9.2.27PE+ABT-737, we looked to the ER, as ABT-737 has been reported to induce the transcription factor ATF4 in other types of cancer." (PMID 21915275, 2011). "For instance, in mutant melanoma with BRAF inhibitor treatment, Grp78 binds the scaffold protein KSR2 to form a multiprotein complex, which acts independently of the UPR to activate ERK and promote the phosphorylation of ATF4." (PMID 38378757, 2024). "For example, it was revealed to be induced in melanoma cells that escaped RAF kinase inhibitor treatment in a recent scRNA-seq study; tumor cells that persisted after treatment with BH3 mimetics similarly depended on ATF4 and the ISR to survive." (PMID 37645713, 2024). "We also report a significant positive correlation between collagen I and ATF4 levels in human tumours and a negative correlation between levels of collagen I with overall survival in patients with melanoma." (PMID 35654839, 2022). "Having observed ATF4 and GADD153 activation in NGLY1-suppressed melanoma cells, we tested whether the relevant signaling similarly alters in NGLY1-deficient COs." (PMID 35322011, 2022). "In the melanoma setting, BRAF inhibitors induce ATF4 translation through two independent signaling pathways: they trigger GCN2 kinase autophosphorylation that activates the canonical ISR, but also can sustain mTOR- and eIF4B-driven ATF4 translation." (PMID 35912100, 2022). "We confirmed host ATF4 deletion by the absence of Atf4 mRNA expression in Atf4Δ/Δ mice across all the host clusters, whereas Atf4 levels remained unchanged in melanoma clusters compared with the Atf4WT/WT mice." (PMID 35654839, 2022). "Moreover, we also found that ATF4 and phosphorylated eIF2α upregulated in PTEN mutant BRAFi-resistant melanoma." (PMID 34282258, 2021). "Although we observed a high recovery of ATF4 after co-treatment of melanoma cells with ACF and MG132, suggesting ATF4 protein stability was reduced by ACF, MG132, per se, is an activator of the unfolded protein response (UPR), making interpretation of this experiment difficult." (PMID 33396270, 2020). "ATF4-mediated NLRP1 expression and IL-1β efflux may be the mechanistic basis for melanoma tumorigenesis and drug resistance via shaping the inflammatory tumor microenvironment." (PMID 33396632, 2020). "The NGLY1 knockdown-induced upregulation of ATF4 and GADD153 was detected in melanoma cells." (PMID 30385822, 2018). "The enhanced phosphorylation of eIF2α was observed in melanoma cells due to the treatment of tunicamycin and NGLY1 knockdown, indicating the activation of the eIF2α signalling as the upstream of ATF4." (PMID 30385822, 2018).